ZWILCH (zwilch kinetochore protein)
Description:
Essential component of the mitotic checkpoint, which prevents cells from prematurely exiting mitosis. Required for the assembly of the dynein-dynactin and MAD1-MAD2 complexes onto kinetochores. Its function related to the spindle assembly machinery is proposed to depend on its association in the mitotic RZZ complex.
Synonyms: hZwilch; FLJ10036; KNTC1AP
Tractability: PROTAC: ubiquitination databases record sites on it.
Gene: Protein-coding gene on chromosome 15 (66,504,959 to 66,550,130, forward strand). Ensembl gene ENSG00000174442.
Subcellular location: Chromosome, centromere, kinetochore
Pathways (Reactome):
Cell Cycle: Amplification of signal from unattached kinetochores via a MAD2 inhibitory signal; EML4 and NUDC in mitotic spindle formation; Mitotic Prometaphase; Resolution of Sister Chromatid Cohesion; Separation of Sister Chromatids
Signal Transduction: RHO GTPases Activate Formins
Gene Ontology:
Molecular function: protein binding
Biological process: mitotic spindle assembly checkpoint signaling; protein localization to kinetochore; regulation of attachment of spindle microtubules to kinetochore
Cellular component: kinetochore; RZZ complex; cytosol; kinetochore microtubule
Genetic constraint (gnomAD): Loss-of-function variants: 39 observed, 48 expected, observed/expected ratio (o/e) 0.81, 90% interval 0.63 to 1.06. The upper end of that interval is the gene's LOEUF score, 1.06, which puts it in group 4 of 6, group 1 being the genes least tolerant of losing a copy. Missense variants: 525 observed, 535.45 expected, observed/expected ratio (o/e) 0.98, 90% interval 0.91 to 1.05. Synonymous variants: 187 observed, 181.18 expected, observed/expected ratio (o/e) 1.03, 90% interval 0.92 to 1.16.
Homologues: Orthologues: macaque ZWILCH (97% identical), chimpanzee ZWILCH (95% identical), pig ZWILCH (87% identical), rabbit ZWILCH (87% identical), dog ZWILCH (87% identical), rat Zwilch (81% identical), mouse Zwilch (81% identical), guinea pig ZWILCH (80% identical), tropical clawed frog zwilch (53% identical), zebrafish zwilch (42% identical), Drosophila melanogaster Zwilch (19% identical), Caenorhabditis elegans zwl-1 (18% identical).
Diseases named in the same sentence as ZWILCH in open-access papers:
ZWILCH is named in the same sentence as 15 diseases in open-access papers, as found by Europe PMC text mining. Sharing a sentence is not in itself a finding about the gene and the disease. The quoted sentences say what the papers report.
colon cancer (3 papers, 2020 to 2023). "The enhanced expression of ZWILCH was detected in many types of cancers: inter alia lung squamous carcinoma, colon cancer, hepatocellular carcinoma, and pancreatic cancer." (PMID 37189849, 2023). "Chen and others (2020) have indicated FANCI and ZWILCH as crucial genes in colon cancer progression and proposed them as potential targets for colon cancer treatment." (PMID 37189849, 2023). "Our results identified FANCI and ZWILCH as critical target genes of colon cancer, suggesting that they might provide a potential pathway for the treatment and intervention of colon cancer." (PMID 32582275, 2020).
adrenal cancer (1 paper, 2023). A carcinoma involving a adrenal gland. "The experiment involved analysis of ZWILCH protein expression with using of commercially available tissue microarrays, containing adrenal tumors (adrenal cancer progression) and normal adrenal gland tissues." (PMID 37189849, 2023).
adrenocortical adenomas (1 paper, 2023). "ZWILCH expression increased in both adrenocortical adenoma (p < 0.05) and adrenocortical carcinoma (p < 0.001) compared with the control group." (PMID 37189849, 2023). "The analysis of the publicly available transcriptomic data from the GEO database shows the expression of the ZWILCH gene in patients with adrenocortical adenomas (n = 22), adrenocortical carcinomas (n = 33), and control group (n = 10)." (PMID 37189849, 2023).
adrenocortical carcinoma (1 paper, 2023). "Our results extend also knowledge of the potential role of ZWILCH in adrenocortical carcinoma conditions." (PMID 37189849, 2023). "The immunohistochemical analysis showed an increased intensity of ZWILCH protein staining in adrenocortical carcinoma, thus confirming the results of our molecular analyses." (PMID 37189849, 2023). "To demonstrate the correlation of ZWILCH expression with other genes and relevant ontological groups, we collected transcriptomic data from ten adrenocortical carcinoma patients with the highest and the lowest ZWILCH expression." (PMID 37189849, 2023). "In further studies, we analyzed ZWILCH gene expression in normal adrenals and adrenocortical carcinoma using our own logical samples." (PMID 37189849, 2023). "In the presented study, we focused on the high-throughput analysis of ZWILCH expression in adrenocortical carcinoma." (PMID 37189849, 2023). "Moreover, we indicated enhanced expression of ZWILCH as an important factor of short survival time among adrenocortical carcinoma patients." (PMID 37189849, 2023). "The upregulation of the ZWILCH gene was observed in many types of cancers, but the association of ZWILCH with adrenocortical carcinoma (ACC) was not investigated so far." (PMID 37189849, 2023).
glioblastoma (1 paper, 2022). The most malignant astrocytic tumor (WHO grade IV). "For the remaining seven DEPCGs (ZWILCH, RPGR, ZNF460, ZNF528, QTRT2, C5orf15 and CNTRL), no previous functional associations were found with glioblastoma progression, despite a number of them being associated with other cancer types." (PMID 36497269, 2022).
lung adenocarcinoma (1 paper, 2023). A carcinoma that arises from the lung and is characterized by the presence of malignant glandular epithelial cells. "Zhang and collaborators (2021) have identified seven N6-methyladenosine-related immune prognostic genes (i.e., PSMD10P1, DIDO1, ABCA5, CIITA, PRC1, ZWILCH, and ANLN) for lung adenocarcinoma (LUAD)." (PMID 37189849, 2023).
multiple myeloma (1 paper, 2023). "In the case of multiple myeloma, all protein-coding genes except for two (ZWILCH and STAG1) are underexpressed." (PMID 37963971, 2023).
myeloma (1 paper, 2023). "In this regard, the finding that every gene in the cell division-associated communities for MM (with the exception of ZWILCH and STAG1) is underexpressed, could mislead to the conclusion that the myeloma cells are not proliferating." (PMID 37963971, 2023).
cancer (3 papers, 2022 to 2023). A tumor composed of atypical neoplastic, often pleomorphic cells that invade other tissues. "It was also proven that the expression of ZWILCH is equal to the Ki67 expression in cancer tissue, and correlates with Weiss score and mitotic tumor rate." (PMID 37189849, 2023). "As the association between ZWILCH and ACC has not been studied before, we discuss our findings in the context of the limited published data on the role of ZWILCH in different types of cancers." (PMID 37189849, 2023). "The low expression of the ZWILCH gene is equal to the decreased expression of KI67 in cancer tissue." (PMID 37189849, 2023). "Furthermore, a significantly positive correlation between the expression of ZWILCH and KI67 in the cancer tissue of the patient (p = 1.1 × 10−13; R = 0.72) was observed." (PMID 37189849, 2023). "Despite ZWILCH expression being investigated in the mentioned types of cancer, its expression has not been studied yet in ACC." (PMID 37189849, 2023).
tumor (1 paper, 2023). "Furthermore, there is a strong correlation between ZWILCH upregulation and tumor mitotic rate and the probability of patient survival." (PMID 37189849, 2023). "Furthermore, there was a strong positive correlation between ZWILCH expression and tumor mitotic rate of (p = 0.0005, R = 0.58)." (PMID 37189849, 2023).
ZWILCH also shares sentences with these, for which no sentence is quoted: adrenal tumors (1 paper); breast carcinoma (1); hepatocellular carcinoma (1); infection (1); pancreatic ductal adenocarcinoma (1).